GLI2 (GLI family zinc finger 2)
Diseases named in the same sentence as GLI2 in open-access papers (continued):
Sharing a sentence is not in itself a finding about the gene and the disease.
pancreatic cancer (27 papers, 2009 to 2025). "In human pancreatic cancer cells, the RNA interference of Gli1 and Gli2 causes β-catenin mis-localization." (PMID 40508185, 2025). "A recent study also showed that gli2-induced overexpression of c-Myc is implicated in pancreatic cancer cell resistance to JQ1 and 1-BET151, selective inhibitors of BET bromodomain proteins." (PMID 28881737, 2017). "For example, GLI2 levels are increased in cells isolated from chemoresistant pancreatic cancer cells." (PMID 40133270, 2025). "GLI2 is reported to contribute to chemoresistance and stemness-related features in adenocarcinoma, pancreatic cancer, and colorectal cancer." (PMID 37950038, 2024). "We also assessed ZEB1 expression in these cells since forced GLI2 expression has been shown to increase ZEB1 expression in pancreatic cancer cells." (PMID 31661013, 2019). "Taken all the data together, we found that acquired gemcitabine resistant pancreatic cancer cells have elevated expression of GLI transcription factors, either GLI1 or GLI2, which is associated with elevated SOX2 expression." (PMID 30382189, 2019). "In this report, we show that pancreatic cancer cells that develop resistance to BET inhibitors upregulate GLI2 and that targeting GLI2 re-sensitizes the pancreatic cancer cells to BET inhibitors." (PMID 25807524, 2015). "Embelin inhibited the expression of Gli1 and Gli2 and their down-stream target Cyclin D1 in mouse pancreatic cancer cells." (PMID 24694877, 2014). "SIBI strongly inhibits gene expression of SHH and downstream target genes such as GLI2 in primary pancreatic cancer cells in vitro." (PMID 23825539, 2013). "The data demonstrate that the components of SHH signaling pathway, including the ligand (Shh), the signaling molecules (Patched-1, Patched-2 and Smoothened) and effectors (Gli1, and Gli2) are expressed in human pancreatic cancer cell lines and pancreatic CSCs." (PMID 22087285, 2011). "Our results highlight the critical role of SHH signaling in human pancreatic CSCs and the possibility of targeting Gli1 and Gli2 activator functions using GDC-0449 in pancreatic cancer stem cells." (PMID 22087285, 2011). "It has previously been reported that pancreatic cancer cells with upregulation of GLI2 and increased expression of markers for epithelial-mesenchymal transition (EMT), which was also enriched in GSEA for HO107, are associated with JQ1 and chemotherapy resistance." (PMID 36256477, 2022). "Down-regulation of GLI1, GLI2 or SOX2 sensitized pancreatic cancer cells to gemcitabine treatment." (PMID 30382189, 2019). "The components of Sonic Hh signaling pathway, including the ligand (SHh), the signaling molecules (Patched-1, Patched-2 and Smoothened) and effectors (Gli1, and Gli2) are aberrantly expressed in human pancreatic cancer cell lines and pancreatic cancer stem cells." (PMID 26369833, 2015). "Since we have previously shown the Shh pathway activation in a panel of human pancreatic cell lines, we also sought to examine the effects of SFN on the expression of Shh receptor (Smothened) and effectors (Gli1 and Gli2) by qRT-PCR in pancreatic cancer cells ASPC and PANC-1." (PMID 23029396, 2012). "Activation of the SHH signaling cascade consistently induces Gli family transcription factors (Gli1 and Gli2), hence both Gli genes mRNA, expressed in pancreatic cancer cell lines and CSCs, stating potential involvement of SHH signaling in human pancreatic carcinogenesis." (PMID 22087285, 2011). "Of particular interest, Smoothened-dependent GDC-0449 treatment of pancreatic CSCs markedly inhibited expressions of SHH receptors (Patched-1, Patched-2 and Smoothened) and effectors (Gli1 and Gli2), thereby showing potential for therapeutic application for treatment of pancreatic cancer." (PMID 22087285, 2011).
pancreatic cancer (continued). "Dual blockade of SMO and BRD4 might also contribute to prevent resistance to pan-selective BET inhibitors such as JQ1, because resistance to JQ1 can be mediated by GLI2-dependent upregulation of cMYC and targeting GLI2 restores JQ1 sensitivity in pancreatic cancer." (PMID 33958721, 2021). "SFN inhibited the expression of Smo, Gli1 and Gli2 in these cell lines as well, suggesting that SFN can inhibit the activation of Shh signaling in pancreatic cancer." (PMID 23029396, 2012). "Notably, the GLI family of HH transcription factors (GLI1, GLI2, GLI3), remain largely unexplored in pancreatic cancer." (PMID 35867772, 2022). "As a result, perturbation of SMO or PTCH1/PTCH2 receptors was not effective to reduce the activation of GLI1/GLI2/GLI3_A in pancreatic cancer model." (PMID 23935937, 2013). "In Pancreatic cancer model, we also observed that GLI2 had higher number of downstream activated proteins compared to GLI1 as it had an activation effect on GLI1, although the Eigenvector centrality of GLI2 was low compared to GLI1." (PMID 23935937, 2013). "The elevation of GLI1 and GLI2 in holoclones suggests higher activity of Hedgehog signaling, which was consistent with the higher level of SHH expression in CD44+CD24+ESA+ cancer stem cells isolated from human primary pancreatic cancer specimens." (PMID 21826251, 2011). "Here we verify in four distinct primary pancreatic cancer cell lines derived from patient tumors that cancer stem cell-enriched sphere cultures indeed show marked overexpression of SHH and the Hedgehog target genes GLI-1 and GLI-2, as well as increased mTOR pathway activity." (PMID 23825539, 2013). "Taken together, we found that elevated GLI1 and GLI2, but not the ligands SHH and IHH, is required for the acquired gemcitabine resistance in pancreatic cancer both in cultured cells and in mice." (PMID 30382189, 2019). "However, these factors are not related to the Wnt-independency phenotype in RNF43-mutant pancreatic cancer, since sgRNAs targeting KDM6A or negative regulators of GLI2 or YAP1, i.e., PTCH1, LATS1, and SAV1, were not enriched in ETC-159 versus vehicle-treated tumors in our initial CRISPR screens." (PMID 35536676, 2022).
basal cell carcinoma (23 papers, 2009 to 2025). A carcinoma involving the basal cells. "KEGG analysis also highlights several pathways associated with disease including “basal cell carcinoma” (Wnt6, Gli2, Wnt10a) and “htlv-i infection” (Smad4, Wnt10a, Prkacb, Wnt6, Tgfbr2) in M. spretus." (PMID 34794440, 2021). "For example, in basal cell carcinoma, loss of Kif3a and cilia has been reported to accelerate Gli2-activated tumor growth." (PMID 26760767, 2016). "On the other hand, silencing the NLRP1 and NLRP3 gene changed the expression of these squamous cell carcinoma proteins marker genes as well as basal cell carcinoma proteins such as Gli1, Gli2, FOXO3A." (PMID 39839625, 2024). "Q-starch/siRNA complexes were examined using siRNA that targets the GLI2 gene in basal cell carcinoma (BCC) cells, overexpressing the GLI2 gene." (PMID 37446506, 2023). "Downregulation of Sam68 impacts the growth and survival of human tumor keratinocytes and genetic ablation of Sam68 delays the onset of basal cell carcinomas (BCC) in Gli2‐transgenic mice." (PMID 31436046, 2019). "In mice, overexpression of SHH, activates SMO, GLI1 or GLI2 and promotes development of basal cell carcinoma like tumors." (PMID 23342114, 2013). "Basal cell carcinomas, induced by an activated form of Smoothened, benefit from the presence of cilia and are suppressed by ciliary ablation, whereas the loss of cilia and lack of Gli2/Gli3 repressor molecules are advantageous for tumors caused by constitutively active Gli2." (PMID 28361305, 2017). "High level of Gli2 expression has been shown in several mouse models, but as mentioned, the overexpression alone is not sufficient to drive MB development, but basal cell carcinoma (BCC) in the skin." (PMID 37608807, 2023).
gastric cancer (22 papers, 2014 to 2025). A primary or metastatic malignant neoplasm involving the stomach. "In gastric cancer, GLI2 has been identified as an intrinsic regulator of programmed cell death ligand 1 (PD-L1) expression in tumor cells that promote tumor growth by inhibiting the anti-tumor response." (PMID 38498906, 2024). "Limited studies suggest that SPOP suppresses tumour development by negatively regulating the Hedgehog/Gli2 signalling pathway in gastric cancer." (PMID 36474188, 2022). "For example, SPOP has a definitive tumour suppressing role in gastric cancer by promoting the degradation of the transcription factor Gli2 of the Hedgehog (Hh)/Gli2 signalling pathway." (PMID 36474188, 2022). "In accordance with qRT-PCR, Western blot (WB) results showed that GLI2 protein was highly expressed in most gastric cancer cell lines, especially in HGC-27 and BGC-823." (PMID 34657624, 2021). "In order to determine the expression of GLI2 in gastric cancer, we firstly detected the GLI2 mRNA in 6 gastric cancer cell lines and immortalized gastric epithelial cell line GES-1." (PMID 34657624, 2021). "The results showed that five miRNA mimics down-regulated GLI2 mRNA expression in at least one gastric cancer cell line, while miR-144-3p down-regulated GLI2 in all the four gastric cancer cell lines." (PMID 34657624, 2021). "Mechanistically, miR-144-3p inhibited gastric cancer progression and stemness via regulating GLI2 expression." (PMID 34657624, 2021). "Next, we explored the expression of GLI2 mRNA in gastric cancer tissues through GEPIA and TCGA databases." (PMID 34657624, 2021). "Through qRT-PCR, we found that GLI2 was up-regulated in most gastric cancer cell lines compared with GES-1." (PMID 34657624, 2021). "What’s more, the correlation between miR-144-3p and GLI2 mRNA expression was analyzed in the gastric cancer tissues of the 21 patients." (PMID 34657624, 2021). "Taken together, our studies indicated that miR‐144-3p inhibited gastric cancer progression and stemness by regulating GLI2 expression." (PMID 34657624, 2021). "Human-derived gastric cancer organoids (huTGOs) that expressed Gli2, not only highly expressed PD-L1, but were also chemoresistant to standard-of-care drugs." (PMID 30647844, 2018). "Collectively, these data suggest that in gastric cancer cells expressing Gli2, inhibition of Hh signaling sensitizes resistance to chemotherapy." (PMID 30647844, 2018). "Here we report a novel, highly-penetrant mouse model of invasive gastric cancer arising from deregulated Hedgehog/Gli2 signaling targeted to Lgr5-expressing stem cells in adult stomach." (PMID 26859571, 2016). "In vitro experiments provide evidence that SPOP functions as a tumor suppressor in different gastric cancer cell lines and contributes to post-transcriptional modification of Gli2." (PMID 25204354, 2014). "Intracellular interaction of SPOP and Gli2 was visualized by immunofluorescent staining in gastric cancer cells." (PMID 25204354, 2014). "Our results indicate that SPOP reduces gastric cancer cell invasion and proliferation by regulating Hh/Gli2 signaling pathway." (PMID 25204354, 2014). "Notably, the activation of HH signaling is a key-driver of resistance to 5-FU in LoVo cells and GLI1 and GLI2 knockdown sensitizes gastric cancer and CRC cells to 5-FU." (PMID 40640948, 2025). "miR-144-3p also inhibits the progression of gastric cancer by directly targeting GLI2." (PMID 37340458, 2023). "MiR-144-3p, for example, inhibited gastric cancer growth and stemness by targeting GLI2." (PMID 35501800, 2022). "GLI2 and miRNAs expression were detected in gastric cancer tissues and cell lines." (PMID 34657624, 2021). "Nevertheless, it was still unclear that whether miR-144-3p inhibited gastric cancer progression via regulating GLI2." (PMID 34657624, 2021). "Finally, our results revealed that miR-144-3p inhibited gastric cancer progression and stemness via targeting GLI2." (PMID 34657624, 2021).
gastric cancer (continued). "The identification of SPOP as a negative regulator of Gli2-mediated transcription may provide an alternative strategy for developing therapeutic agents for gastric cancer in future." (PMID 25204354, 2014). "Therefore, attempting to block or silence the expression of GLI2 will significantly help to suppress gastric cancer progression, and thus GLI2-targeted miRNA might be a good choice for gastric cancer treatment." (PMID 34657624, 2021). "Therefore, we wondered that whether there were miRNAs which directly target GLI2 and thus inhibited the progression of gastric cancer." (PMID 34657624, 2021). "Importantly, this study provided unexcepted evidence that higher GLI2 expression could be a favorable prognostic marker, and Beclin1 acted as a tumor suppressor in gastric cancer." (PMID 30081498, 2018). "Hence, this study postulated that autophagy may be related to Hh signaling in gastric cancer, and together, Beclin1 and GLI2 expression level is a possible prognostic biomarker." (PMID 30081498, 2018). "Then, alive and dead assay is performed, and results show that down-regulation of GLI2 enhances the cell toxicity of CAPE in colorectal and gastric cancer cell lines." (PMID 38159250, 2023). "Therefore, we synthesized the miRNA mimics of these seven candidates and transferred them into four gastric cancer cell lines (HGC-27, BGC-823, SGC-7901, and MGC-803) respectively, and the changes of GLI2 mRNA were detected by qRT-PCR." (PMID 34657624, 2021). "Besides that, Gli2 induces transcription of PDGFRB and promotes cancer stem cell properties in gastric cancer." (PMID 32493490, 2020). "Moreover, there was a significant negative correlation between miR-144-3p and GLI2 mRNA expression in 372 gastric cancer samples in TCGA (Pearson r = − 0.275, p < 0.001)." (PMID 34657624, 2021).
colorectal cancer (21 papers, 2014 to 2025). A primary or metastatic malignant neoplasm that affects the colon or rectum. "HIF-1α/TGF-β2/GLI2 expression promotes stemness and chemoresistance in colorectal cancers and is associated with patient relapse following chemotherapy." (PMID 31244888, 2019). "The G-protein-coupled receptor 126 (GPR126) engendered increased transcription and translation of histone deacetylase 2 (HDAC2), which regulated Gli2 expression and enhanced colorectal cancer cell proliferation." (PMID 40170839, 2025). "For instance, in colorectal cancer, the hypoxic tumor microenvironment activates the expression of GLI2 in CSCs, resulting in increased stemness/dedifferentiation and intrinsic resistance to chemotherapy." (PMID 37953246, 2023). "Hypoxia induces TGF-β2 secretion from CAFs and activates HIF-1α to transcriptionally upregulate the expression of GLI family zinc finger 2 (GLI2) in colorectal cancer stem cells." (PMID 35884382, 2022). "This study not only presents evidence for understanding the contribution of Hh to colorectal cancers, but also provides a novel molecular portrait underlying how PGE2-activated JNK fine-tunes the evasion of Gli2 from ubiquitin-proteasomal degradation." (PMID 34267186, 2021). "PGE2 treatment of colorectal cancer cells increased the abundance of Gli1 and Gli2 proteins, reaching maximum at approximately 1 h, with no appreciable effect on the expression of Gli3 protein." (PMID 34267186, 2021). "In colorectal cancer, hypoxia-inducible factor (HIF-1α) and cancer-associated fibroblasts (CAFs)-secreted TGF-β2 converge to induce strong expression of GLI2 in CSCs, independently of HH signaling." (PMID 31244888, 2019). "Additionally, we examined the correlation between HOTTIP and GLI2 expression and the pathological features of colorectal cancer tissues." (PMID 40624028, 2025). "In colorectal cancer, cancer-associated fibroblasts (CAFs)-secreted TGFB2 and hypoxia-inducible factor (HIF-1α) interact to activate the expression of hedgehog transcription factor GLI2 in cancer stem cells, resulting in intrinsic resistance to chemotherapy." (PMID 38914663, 2024). "Additionally, GLI2 induced chemoresistance in colorectal cancer through HIF-1α and TGF-β2 signaling pathways." (PMID 37280069, 2023). "Our group recently demonstrated that prostaglandin E2-induced activation of c-Jun N-terminal kinase (JNK) increased GLI2 expression in a SMO-independent mechanism through phosphorylating GLI2 at Thr1546, which is important for colorectal cancer cell proliferation." (PMID 37213270, 2023). "Further investigation reveals that LINC01106 located in the nuclear could recruit FUS protein to Gli1 and Gli2 promoters, hence activating Gli1 and Gli2 transcription and promoting colorectal cancer formation." (PMID 35581586, 2022). "Taken together,these data demonstrate that colorectal cancer cells may hijack PGE2 to enable the evasion of Gli2 from ubiquitin proteasomal degradation by activating JNK." (PMID 34267186, 2021). "Hence, This study not only presents evidence for understanding the contribution of Hh to colorectal cancers, but also provides a novel molecular portrait underlying how PGE2-activated JNK fine-tunes the evasion of Gli2 from ubiquitin-proteasomal degradation." (PMID 34267186, 2021). "We next continued to explore whether JNK-mediated Gli2 Thr1546 phosphorylation is essential for Hh activity and proliferation of colorectal cancer cells in response to PGE2." (PMID 34267186, 2021). "Collectively, these data obtained from ApcMin/+ mice further confirmed that PGE2-JNK signaling axis may non-canonically promote Hh activity in a Smo-independent manner by protecting Gli2 from degradation, and consequently promote the development of colorectal cancer growth." (PMID 34267186, 2021).
colorectal cancer (continued). "In colorectal cancer, LINC01106 is highly expressed and enhances proliferation, migration, and stem-like characteristics of colorectal cancer cells via STAT 3 and LINC01106/Gli2 positive feedback loop." (PMID 39735666, 2025). "In patient-derived xenografts colorectal cancer models, CAFs-secreted growth factor TGF-β2 directly induced transcription of GLI2, thereby contributing to increasing stemness and intrinsic resistance to chemotherapy." (PMID 37213270, 2023). "In summary, this study demonstrate PGE2 non-canonically promotes Hh pathway activity by suppressing the ubiquitination of Gli2 through JNK, thereby promoting the progression of colorectal cancers." (PMID 34267186, 2021). "Experimental studies have confirmed that phosphorylated c-Jun, activated by kinase JNK, prevents Gli2 from undergoing proteasomal-ubiquitin degradation through the PGE2-JNK signaling axis, thereby promoting Hh activation and colorectal cancer cell proliferation." (PMID 40170839, 2025). "Recent studies have also confirmed that PARK7 promotes the proliferation and metastasis of colorectal cancer by activating the Hh and Wnt signaling pathways, and that PARK7 increases proteins involved in the Hh signaling pathway, including GLI1, GLI2, and PTCH1." (PMID 39276379, 2024). "Results shows that higher expression of GLI2 is related to worse prognosis in READ, both in the TCGA cohort and GEO cohort, and the expression level of GLI2 is higher in colorectal cancer tissues as compared with normal tissues (p < 0.001)." (PMID 38159250, 2023). "Hence, these results showed that JNK-mediated Gli2 Thr1546 phosphorylation is required for the PGE2-dependent Hh activity and proliferation of colorectal cancer cells." (PMID 34267186, 2021). "Examination of the tissue array of human colorectal cancer and adjacent non-tumor tissues with IHC staining revealed the increased expression of Gli2, p-JNK, p-Gli2T1546, and ki-67 compared with those in adjacent non-tumor tissues." (PMID 34267186, 2021). "Comparable to the elevated Gli activity, PGE2 increased the proliferation of all of these tested colorectal cancers cells in a Gli-dependent manner, as revealed by the inhibitory effect of either Gli inhibitors GANT61 and JQ1, or genetic silencing Gli2 by small interfering RNA (siRNA)." (PMID 34267186, 2021). "However, we found GLI2 and GLI3 were barely detectable in colorectal cancer cells." (PMID 35359953, 2022).